ST6GAL1 (ST6 beta-galactoside alpha-2,6-sialyltransferase 1)
Diseases named in the same sentence as ST6GAL1 in open-access papers (continued):
Sharing a sentence is not in itself a finding about the gene and the disease.
colorectal cancer (16 papers, 2009 to 2025). A primary or metastatic malignant neoplasm that affects the colon or rectum. "In summary, our study highlights the upregulation of ST6GAL1 in colorectal cancer (CRC) and its strong association with tumor progression, suggesting its potential as a therapeutic target." (PMID 40847469, 2025). "β-Galactoside α-2,6-sialyltransferase 1 (ST6Gal1) catalyzes EGFR sialylation that is associated with gefitinib resistance in colorectal cancers, and this was also investigated." (PMID 30187356, 2018). "ST6 β-galactoside α2,6-sialyltransferase 1 (ST6GAL1), a crucial enzyme for tumor-associated sialic acid modification, has been reported to positively correlate with colorectal cancer (CRC) tumorigenesis; however, the underlying mechanism remains unclear." (PMID 39937175, 2025). "Furthermore, elevated levels of ST6Gal1 in the colorectal cancer cell lines Caco-2 and SW48 were associated with increased expression of WNT3a and β-catenin as well as fluorouracil (5-FU) resistance." (PMID 36106023, 2022). "ST6GAL1 plays a critical role in tumor progression and immune regulation in colorectal cancer (CRC)." (PMID 40847469, 2025). "ST6GAL1‐mediated sialylation of PD‐L1 is critical for maintaining its stability in colorectal cancer cells, and ST6GAL1 knockdown leads to reduced protein stability and increased ubiquitination." (PMID 40847469, 2025). "Although most of the current studies recognize the tumor promoting role of ST6GAL1, few reports suggest opposite function in colorectal cancer." (PMID 33921986, 2021). "NDAT enhancedd gefitinib-induced antiproliferation in gefitinib-resistant colorectal cancer cells by inhibiting ST6Gal1 activity and PI3K activation." (PMID 30187356, 2018). "Studies elsewhere also have shown that SW480 colorectal carcinoma cells with ST6Gal1-knockdown are sensitive to gefitinib." (PMID 30187356, 2018). "In addition, it is reported that upregulation of ST6GAL1 led to metastasis and spread of human colorectal cancer (CRC) cells." (PMID 37132100, 2023). "ST6GAL1 is also negatively regulated by miR-214 in colorectal cancer cells." (PMID 33921986, 2021). "On the other hand, NDAT inhibited ST6Gal1 expression in both colorectal cancer cell cultures." (PMID 30187356, 2018). "To address this aspect, we performed colocalization experiments of the enzymes involved in our predicted reactions, namely B4GalT1, MGAT3, and ST6Gal1, in kidney COS-7 cells and CaCo-2 colorectal cancer cells." (PMID 29133956, 2017). "This analysis identified five glycosyltransferase genes, namely, ST6GAL1, GALNT6, HPSE, GALNT1, and GALNT7, expression of which was consistently upregulated or downregulated in MSI colorectal cancer tissues, cell lines, and single epithelial cells compared with MSS colorectal cancers." (PMID 40824763, 2025). "We found that NDAT blocked ST6Gal1-induced sialylation of EGFR and consequent PI3K activation, which are essential for proliferation of cancer cells in both K-ras wild-type (wt) and K-ras mutant colorectal cancer cells." (PMID 30187356, 2018).
prostate carcinoma (14 papers, 2009 to 2025). A carcinoma that arises from epithelial cells of the prostate gland. "The enzyme ST6 β-galactoside α2,6-sialyltransferase 1 (ST6GAL1) mediates α2,6-linked sialylation of N-glycosylated proteins and is upregulated in many cancers, including prostate cancer (PrCa)." (PMID 40938891, 2025). "Together with the findings above, these data suggest the mechanisms underlying the role of ST6GAL1 in prostate cancer are multi-faceted, and also likely involve the regulation of immunosuppressive sialoglycans that can engage immune cells." (PMID 38772281, 2024). "ST6GAL1 is overexpressed in numerous types of cancer, including pancreatic, breast, ovarian and prostate cancer, and is associated with aggressive disease and poor patient prognosis." (PMID 38772281, 2024). "The sialyltransferase ST6GAL1 has been previously identified to be upregulated in prostate cancer and linked with tumour growth, metastasis, and poor overall survival." (PMID 39272811, 2024). "Based on this, it is tempting to propose an additional mechanism underlying the role of ST6GAL1 in prostate cancer – the regulation of immunosuppressive sialylated glycans." (PMID 38772281, 2024). "ST6GAL1 is upregulated in numerous types of cancer, including pancreatic, ovarian, breast, and prostate cancer, and its expression is associated with aggressive tumours and reduced survival times." (PMID 39272811, 2024). "However, although ST6GAL1 has been linked to more aggressive prostate tumours, to our knowledge the in vivo role of ST6GAL1 and sialylated N-glycans in prostate cancer metastasis remains a critical knowledge gap." (PMID 38772281, 2024). "Taken together, our data suggests ST6GAL1 may be upregulated in patients with prostate cancer that have increased risk of metastasis, those developing relapse to castrate-resistant disease, and patients with prostate tumours that have spread to the bone." (PMID 38772281, 2024). "Shedding of glycosyltransferases from cells has previously been reported and we recently identified upregulation of the glycosyltransferase enzymes GALNT7 and ST6GAL1 in the blood of prostate cancer patients." (PMID 40387385, 2025). "In prostate cancer (PrCa), ST6GAL1 levels are elevated in patient plasma, and ST6GAL1 expression positively correlates with Gleason score, seminal vesicle involvement, and poor survival." (PMID 40938891, 2025). "ST6GAL1 is upregulated in patients with prostate cancer with tumours that have spread to the bone and can promote prostate cancer bone metastasis in vivo." (PMID 38772281, 2024). "Next, to investigate how ST6GAL1 changes prostate cancer cell behaviour towards a more metastatic biology, we used RNA-sequencing (RNA-Seq) of PC3 and DU145 prostate cancer cells." (PMID 38772281, 2024). ",20, 21, 22 We recently showed that ST6GAL1 levels are increased in the blood of men with prostate cancer and that upregulation of ST6GAL1 can promote prostate cancer cell invasion and tumour growth." (PMID 38772281, 2024). "Using quantitative PCR, we analysed ST6GAL1 gene levels in a molecular subgroup of patients with prostate cancer that have metastatic potential at presentation (previously published by25,53)." (PMID 38772281, 2024). "Sialylated glycans can be engaged by a broad range of immune cell types to promote immune suppression, and the upregulation of ST6GAL1 in prostate cancer cells has been shown to promote a shift towards an immunosuppressive M2 macrophage phenotype." (PMID 39272811, 2024). "Our findings show that conditioned media from prostate cancer cells overexpressing ST6GAL1 cells can promote primary murine monocyte/macrophage like cells to differentiate into osteoclasts (unpaired t test, p = 0.0013)." (PMID 38772281, 2024). "It is evident that ST6GAL1-mediated sialylation plays a central role in prostate cancer tumour pathology and metastasis, and thus holds huge potential for the development of new therapeutics." (PMID 38772281, 2024).
prostate carcinoma (continued). "In previous studies, we detected increased levels of α2,6 sialylation in prostate cancer cells with an upregulation of ST6GAL1." (PMID 39272811, 2024). "In prostate cancer, the upregulation of ST6GAL1 promotes the growth and metastatic spread of prostate tumours to bone, and targeting aberrant sialylation in prostate cancer cells can inhibit the metastatic spread of tumours to bone." (PMID 39272811, 2024). "We recently showed ST6GAL1 is upregulated in blood samples from men with prostate cancer, compared to men with either benign disease or men given a ‘no cancer’ diagnosis." (PMID 38772281, 2024). "Here, we monitor ST6GAL1 in tumour and serum samples from men with aggressive prostate cancer and using in vitro and in vivo models we investigate the role of ST6GAL1 in prostate cancer bone metastasis." (PMID 38772281, 2024). "Inhibitors specifically targeting ST6GAL1 are being developed and, once available, will be highly relevant to prostate cancer." (PMID 39272811, 2024). "Our findings reveal expression of ST6GAL1 alters sialoglycan patterns in prostate cancer cells, and in line with the literature, we find ST6GAL1 specifically regulates sialoglycans that engage Siglec-2 (CD22) and Siglec 3 (CD33)." (PMID 38772281, 2024). "Of particular interest, we also detected increased secretion of colony-stimulating factor-1 (CSF1) in prostate cancer cells overexpressing ST6GAL1." (PMID 38772281, 2024). "Our findings identify ST6GAL1-mediated aberrant sialylation as a potential mediator of acquired resistance to enzalutamide therapy in prostate cancer." (PMID 39272811, 2024). "Here, using VCaP and LNCaP cell line models, we show that prostate cancer cells with acquired resistance to enzalutamide have upregulated ST6GAL1 and significantly higher levels of α2-6 sialylated N-glycans." (PMID 39272811, 2024). "Previous studies have identified increased levels of ST6GAL1 in tumours and blood samples from prostate cancer patients." (PMID 39272811, 2024). "Here, using patient tissue samples, cell culture studies, and animal cancer models we show that ST6GAL1 is upregulated in men with prostate cancer bone metastasis, and reveal aberrant sialylation can promote the spread of prostate cancer to bone." (PMID 38772281, 2024). "Our findings suggest ST6GAL1 is 2.3-fold upregulated in patients with prostate cancer bone metastasis compared to patients with localised disease (unpaired t test, p = 0.0091)." (PMID 38772281, 2024). "Recently, we showed that ST6 beta-galactoside alpha-2,6-sialyltransferase 1 (ST6GAL1) and larger branched sialylated N-glycans are upregulated in men with prostate cancer, and this can promote tumour growth and the spread of tumours to bone." (PMID 39272811, 2024). "To address this gap, we used western blotting and pre-validated sandwich ELISA assays to monitor ST6GAL1 protein levels in VCaP and LNCaP prostate cancer cell line models with acquired resistance to enzalutamide." (PMID 39272811, 2024). "Next, using immunohistochemistry (IHC) we analysed ST6GAL1 levels in a 96 case tissue microarray (TMA) comprising tissue from patients with prostate cancer diagnosed with tumours of different Gleason grades." (PMID 38772281, 2024). "Here, we find ST6GAL1 is upregulated in blood and tissue samples from patients with prostate cancer that have tumours which have spread to the bone and show that ST6GAL1 can promote prostate cancer metastasis in vivo." (PMID 38772281, 2024). "Taken together, these findings suggest that the sialyltransferase ST6GAL1 is upregulated in prostate cancer cells with acquired resistance to enzalutamide therapy." (PMID 39272811, 2024). "In prostate cancer, the sialyltransferase ST6GAL1 is upregulated, and studies show ST6GAL1-mediated aberrant sialylation of N-glycans promotes prostate tumour growth and disease progression." (PMID 38772281, 2024).
prostate carcinoma (continued). "Decreased expression of ST6Gal1 in prostate cancer models results in diminished activation of a PI3K/AKT/GSK-3β signaling axis, leading to diminished β-catenin." (PMID 36106023, 2022). "AOS has been recently shown to inhibit the expression of ST6GAL1 in human prostate cancer cells via the Hippo/YAP pathway, leading to altered expression profile of α-2,6-linked sialic acids." (PMID 33921986, 2021). "In prostate cancer cells, ST6GAL1 silencing inhibited cell migration and invasion through downregulation of the PI3K/AKT/GSK-3β/β-catenin pathway." (PMID 33921986, 2021). "Progression of prostate cancer was promoted by the increase of α2,6-sialylated-glycans via the overexpression of ST6GAL1." (PMID 31795149, 2019). "The data presented reveals ST6GAL1 controls the expression sialoglycans on prostate cancer cells including ligands that could engage Siglec-2 (CD22) and Siglec-3 (CD33) on immune cells." (PMID 38772281, 2024). "To address this gap, we here monitored ST6GAL1 in five additional prostate cancer clinical cohorts." (PMID 38772281, 2024). "The findings presented suggest that upregulation of ST6GAL1 in prostate cancer cells could promote CD206+ M2 macrophages which could contribute to the relative resistance of bone metastatic CRPC to immune checkpoint therapy." (PMID 38772281, 2024). "Together, our data suggests that levels of both ST6GAL1 and larger branched α2-6 sialylated tri-antennary and tetra-antennary N-glycans remain high in prostate cancer cells after they have disseminated from the primary site and established metastatic lesions in bone." (PMID 38772281, 2024). "In prostate cancer, ST6GAL1-mediated aberrant sialylation promotes tumour growth and is linked to disease progression, but the role of ST6GAL1 and sialylated N-glycans in prostate cancer metastasis has not yet been investigated." (PMID 38772281, 2024). "We thus hypothesised that the upregulation of ST6GAL1 in enzalutamide-resistant prostate cancer cells will alter the levels of α2,6 sialylated N-glycans." (PMID 39272811, 2024). "In summary, our findings confirm blood borne ST6GAL1 levels are increased in men diagnosed with prostate cancer, and further show levels of ST6GAL1 are significantly higher in the blood of men with more aggressive prostate tumours, and upon relapse to metastatic castrate resistant disease." (PMID 38772281, 2024). "In conclusion, here we show that the sialyltransferase enzyme ST6GAL1 is upregulated in tumours and blood samples from patients with prostate cancer bone metastasis and that ST6GAL1-mediated aberrant sialylation can promote the spread of prostate tumours to bone." (PMID 38772281, 2024). "When serum ST6GAL1 levels were compared in men with low grade and high grade prostate cancer (Gleason grade 6–7 compared to Gleason grade 8–9), levels of ST6GAL1 were found to be 6.7-fold higher in men with higher grade compared to men with lower grade disease (n = 200, unpaired t test, p < 0.0001)." (PMID 38772281, 2024). "In addition to promoting osteoclasts in the pre-metastatic niche, our data also suggests that ST6GAL1 enhances the development of M2 like macrophages and can also regulate sialoglycans on prostate cancer cells that engage Siglec receptors." (PMID 38772281, 2024). "Excitingly, our data shows that upregulation of ST6GAL1 in prostate cancer cells significantly increases expression of CD206 on macrophages, suggesting a shift toward a more immunosuppressive M2 phenotype (Two-way ANOVA, p < 0.0001) which was not dependent upon CSF1." (PMID 38772281, 2024). "Our findings identify a potential role for ST6GAL1-mediated aberrant sialylation in acquired resistance to enzalutamide therapy for prostate cancer and suggest that sialic acid blockade in combination with enzalutamide may represent a novel therapeutic approach in patients with advanced disease." (PMID 39272811, 2024).
prostate carcinoma (continued). "Furthermore, we find the role of ST6GAL1 in aggressive prostate cancer likely involves modification of the bone pre-metastatic niche towards bone resorption to promote the vicious cycle, the promotion of M2 like macrophages and the regulation of immunosuppressive sialoglycans." (PMID 38772281, 2024). "Furthermore, factors secreted by ST6GAL1 overexpressing prostate cancer cells may promote the development of TAMs and contribute to an immunosuppressive TME." (PMID 38772281, 2024). "However, to date, studies investigating the role of ST6GAL1 and its associated glycans in therapy-resistant prostate cancer are lacking." (PMID 39272811, 2024). "Consistent with ST6GAL1 regulating Siglec-2 and Siglec-3 ligands, we also detected downregulation of sialoglycans that engage Siglec-2 and Siglec-3 in murine RM1 prostate cancer cells depleted of ST6GAL1." (PMID 38772281, 2024). "Through suppression of the PI3K/AKT/GSK-3/-catenin pathway, ST6GAL1 silencing reduced the capacity of PC-3 and DU145 prostate cancer cell lines to proliferate and form colonies." (PMID 36547200, 2022). "ST6GAL1 silencing attenuated proliferation and colony formation ability of PC-3 and DU145 prostate cancer cell lines, through inhibition of the PI3K/AKT/GSK-3β/β-catenin pathway." (PMID 33921986, 2021). "Of 31 reciprocally-regulated glycosylation enzymes, a set of 8 (GALNT7, ST6GalNAc1, GCNT1, UAP1, PGM3, CSGALNACT1, ST6GAL1 and EDEM3) were significantly up-regulated in clinical prostate carcinoma." (PMID 27428423, 2016). "In agreement with our previous findings, ST6GAL1 serum levels were 7.3-fold higher in men diagnosed with prostate cancer relative to men without prostate cancer (n = 240, unpaired t test, p < 0.0001)." (PMID 38772281, 2024). "ST6GAL1 has been reported as a mediator of therapy resistance in other cancer types, but a link between ST6GAL1 and resistance to therapy has not yet been investigated for prostate cancer." (PMID 39272811, 2024). "Furthermore, in the prostate cancer cell lines, PC-3 and DU145, cell proliferation along with PI3K/ALK signaling was reduced when the ST6Gal1 gene was silenced." (PMID 36106023, 2022). "Here, using cell line models, we show that prostate cancer cells with acquired resistance to enzalutamide therapy have an upregulation of the sialyltransferase ST6 beta-galactoside alpha-2,6-sialyltransferase 1 (ST6GAL1) and increased levels of α2,6-sialylated N-glycans." (PMID 39272811, 2024). "However, to date the in vivo role of ST6GAL1 in prostate cancer metastasis has not yet been investigated." (PMID 38772281, 2024). "Within this dataset, ST6GAL1 is 6.3 -fold upregulated in the ‘metastatic’ subgroup compared to the ‘non-metastatic’ sub-group, suggesting upregulation of the ST6GAL1 gene in patients with primary prostate cancer presenting with metastatic biology (n = 20, unpaired t test, p = 0.024)." (PMID 38772281, 2024).
hepatocellular carcinoma (11 papers, 2016 to 2024). A malignant tumor that arises from hepatocytes. "ST6Gal1 was also associated with changes in PI3K/AKT signaling in hepatocellular carcinoma (HCC)." (PMID 36106023, 2022). "ST6GAL1 inhibits metastasis of hepatocellular carcinoma via modulating the sialylation of MCAM on the cell surface." (PMID 38274327, 2024). "sEV-mediated proliferation and migration of recipient human hepatocellular carcinoma cells were inhibited by the reduction of sialic acid level on sEV through ST6Gal-1 knockdown in donor cells." (PMID 38561669, 2024). "In order to determine if B cell secreted ST6GAL1 is capable of extrinsically remodeling cell surfaces, we applied concentrated conditioned medium from Louckes cells (concentrated ~20X) to sialidase-pretreated human hepatoma HepG2 cells." (PMID 31408003, 2019). "In hepatocellular carcinoma, miR-195-3p contributes to OXP-resistance through the TINCR/miR-195-3p/ST6GAL1/NF-κB signaling axis." (PMID 39401197, 2024).